VDAC1P1 (voltage dependent anion channel 1 pseudogene 1)
Synonyms: formerly VDAC1P
Gene: Processed pseudogene on chromosome X (80,929,500 to 80,930,347, forward strand). Ensembl gene ENSG00000073905.
Diseases named in the same sentence as VDAC1P1 in open-access papers:
VDAC1P1 is named in the same sentence as 5 diseases in open-access papers, as found by Europe PMC text mining. Sharing a sentence is not in itself a finding about the gene and the disease. The quoted sentences say what the papers report.
breast carcinoma (1 paper, 2023). "In contrast, VDAC1P1 appears to be associated with lamin B1 (LMNB1) transcription factor, which is known to be overexpressed in several cancers, such as lung adenocarcinoma, breast cancer and leukemia." (PMID 37344914, 2023).
tumor (1 paper, 2023). "Specifically, the expression profile of VDAC1P1 and VDAC1P2 in this analysis largely mirrors that of VDAC1, in both healthy and tumor tissues." (PMID 37344914, 2023).
VDAC1P1 also shares sentences with these, for which no sentence is quoted: cancer (1 paper); leukemia (1); lung adenocarcinoma (1).